KRAS (KRas proto-oncogene, GTPase)
Diseases named in the same sentence as KRAS in open-access papers (continued):
Sharing a sentence is not in itself a finding about the gene and the disease.
tumor (continued). "This suggested that beta-elemene may inhibit tumor growth by inducing ferroptosis in KRAS mutant colorectal cancer cells." (PMID 36193068, 2022). "Our study results showed significant associations between genetic variations and age (EGFR L858R), gender (EGFR exon 19 deletion, L858R), smoking history (EGFR L858R, exon 20 insertion, and KRAS mutation), histological type (EGFR exon 19 deletion, L858R), and tumor grade (ALK fusion)." (PMID 35061839, 2022). "Moreover, we observed significantly lower aneuploidy scores (total number of arm-level gains and losses in a tumor) in KRAS-Mut versus WT tumors (P = 0.038)." (PMID 35836817, 2022). "Indeed, preclinical evidence pointed out a significant reduction of tumor growth when afatinib was combined with anti-KRAS molecules." (PMID 36358848, 2022). "Of note, among the downregulated pathways are comprised KRAS, Hypoxia, and Epithelial Mesenchymal Transition, all related to the tumorigenic process, providing further support to the overall effect of impairing cell proliferation and tumor growth." (PMID 36552757, 2022). "Oncogenic KRAS is associated with increased phospho-extracellular signal-regulated kinase (ERK), which plays a crucial role in the proliferation, survival, and development of tumor cells." (PMID 36077614, 2022). "Besides upregulating the transcriptional activity of the PD-L1 gene, KRAS-mutant tumor cells were also shown to be able to increase PD-L1 mRNA stability via MAPK-dependent signaling." (PMID 35965494, 2022). "Data from intraductally transplanted orthotopic xenografts using patient-derived organoids also implicates KRAS amplification in promoting squamous-like, invasive features within heterogeneous tumours, since inducible genetic activation of KRAS promotes an invasive phenotype in these models." (PMID 36088504, 2022). "The prognostic and predictive value of KRAS in these rare tumor subtypes deserves further study." (PMID 35359599, 2022). "However, no (L)PVs were detected in the other two most frequently mutated genes, KRAS and ARID1A, in either tumor." (PMID 36291559, 2022). "Comparison of EGFR L858R, EGFR exon 20 insertion, KRAS mutation, histological type, and tumor grade between smoker and non-smoker in different gender, and between male and female patients in smokers or non-smokers." (PMID 35061839, 2022). "However, in another study related to oncogenic KRAS, KRAS mutations triggered enhanced ADAM17-mediated NPG1 shedding of the SLC3A2-NPG1 fusion protein, which in turn promoted tumor cell growth." (PMID 36466812, 2022). "SLC1A5 has been regarded as an oncogene by the mTORC1 signaling pathways or KRAS mutation in certain tumors, and loss of SLC1A5 may inhibit tumor growth." (PMID 36262284, 2022). "This analysis of pre- and posttreatment tumors uncovered cancer cell–intrinsic and –extrinsic features of resistance, including reactivation of KRAS-mediated signaling, reprogramming of metabolism, epithelial-mesenchymal transition, and tumor microenvironment changes." (PMID 35166243, 2022). "More recently, KRAS mutational status within the resection margins of resected tumours from 81 patients with or without neoadjuvant therapy (NAT) was prognosis of recurrence-free survival." (PMID 35194118, 2022). "Also, in SK-LU1 xenografted mice, the application of the αEGFR-mAB-P/KRAS-siRNA/P nanostructures reduced tumour sizes and weights by about 50% when compared with the control-treated groups." (PMID 35220407, 2022).
tumor (continued). "Constitutive activation of KRAS and persistent stimulation of downstream pathways sustains tumor cell proliferation, migration, metastasis and metabolic reprogramming, along with the evasion of the anti-tumor immune response." (PMID 35681634, 2022). "For example, the unique properties of lysosomes (pH, composition, abundance and degradation activity of lysosomal hydrolase, etc.)of KRAS mutant tumor cells, if any, could guide us in designing conditional active drug delivery systems." (PMID 35154489, 2022). "Furthermore, in CRCs, KRAS mutation can induce GM-CSF in the TME through enhancing the infiltration of MDSCs, causing a reduction in anti-tumor immunity." (PMID 36430176, 2022). "Dual MET/KRAS (G12C) inhibition resulted in tumor shrinkage in AMG510-resistant xenograft mice." (PMID 35922812, 2022). "This could indicate that parts of the tumor with the most actively proliferating cells were least impacted by KRAS-driven inflammation, or that tumor cells modulate their KRAS-driven associated inflammation during proliferation." (PMID 35995947, 2022). "Moreover, OCs can be divided in type I (low-grade tumor with BRAF and KRAS mutations) or type II (high-grade tumor with a variety of mutations including HOX, PTEN, KRAS, AKT1, BRCA1/2 genes) and various dysregulated mechanisms underlying the pathology." (PMID 36191006, 2022). "Thus it was shown that cetuximab-based therapy resulted in better outcomes in patients with left- compared to right-sided tumours KRAS wild-type mCRC." (PMID 35637412, 2022). "The cell lines differ in their KRAS/BRAF mutational status and primary tumor or metastasis origin." (PMID 35897809, 2022). "Co-inhibition of FGFR and MAPK pathway by FGFR inhibitors and MEK inhibitor Trametinib induced tumor degradation in tumor xenografts derived from mesenchymal-like KRAS mutant cancer cell lines as well as patient-derived xenograft model with a typical mesenchymal phenotype." (PMID 33568192, 2021). "Enhanced chemosensitivity of tumor cell lines with defective KRAS may represent a link to these observations." (PMID 33909629, 2021). "We propose that pharmacological targeting of tricarboxylic acid (TCA) cycle in hypoxic and hard-to-treat neoplasias may constitute a novel approach in the treatment and/or chemosensibilization of KRAS driven tumors." (PMID 33664850, 2021). "Further work is needed to elucidate the likely complex cell-autonomous and non-autonomous effects of mutated and unmutated KRAS protein on the tumor microenvironment." (PMID 34607583, 2021). "A secondary screen using the top 52 hits from the primary screen was performed to evaluat the ability to kill a panel of 28 tumor cell lines from various cancer types, comprising 14 that carried an activating KRAS mutation and 14 that did not." (PMID 34065438, 2021). "However, miR-27b is downregulated in colon cancer by c-SRC and KRAS, suggesting a tumor suppressive role." (PMID 33572600, 2021). "What type of anti-tumour therapies are worth using in KRAS mutant cancer cells?" (PMID 33925206, 2021). "Tumor DNA analysis identified (a) a stop codon leading to loss of function of protein NOTCH1 (p.Q290*) and (b) a genomic amplification of KRAS, which results in overexpression of KRAS protein, activation of KRAS-MAPK pathway, and tumor progression." (PMID 33466719, 2021).
tumor (continued). "ROS is a product of mutant-KRAS signaling, which is involved in various metabolic processes and may thereby be a pro-tumor factor." (PMID 33819918, 2021). "By analyzing the data of 66 patients with CRC, the SUVmax was found not to be related to the tumor-node-metastasis stage, clinical stage, sex, and KRAS mutation but was related to the tumor location and nerve invasion." (PMID 34956868, 2021). "The design of targeted therapies is reliant upon understanding how mutant KRAS alters tumor cells." (PMID 33855169, 2021). "To verify whether the selective advantage of tumor cells to reprogram TAMs is determined by their KRAS status, we disrupted KRAS signaling using a KRAS-specific siRNA pool in SW620 cells." (PMID 33833221, 2021). "Striking phenotypic changes were apparent in both KRAS KO tumor cells and stromal cells." (PMID 33674596, 2021). "KRAS status concordance between tumor specimens and matched plasma samples was 100%." (PMID 35582309, 2021). "Our data show that KRAS ablation increases the influx of immune cells into the tumor, but with higher immune checkpoint expression that may be able to suppress the adaptive T-cell response." (PMID 33674596, 2021). "Beyond providing insight on tumor protein expression, our detection of mutant KRAS genes in CHCs isolated from a patient with PDAC highlights their promise as source of genomic material to facilitate tumor profiling for clinically actionable oncogenic alterations." (PMID 34211050, 2021). "The combination of a Unc-51 Like Autophagy Activating Kinase 1 (ULK1) inhibitor, MRT68921, with an anti-PD-1 monoclonal antibody can increase antigen presentation and therefore restore anti-tumor immunity, by compensating for LKB1 loss, leading to KRAS/LKB1 co-mutant tumor regression." (PMID 34944952, 2021). "This study evaluated 41 patients with MET-high, KRAS wild-type mCRC, who were treated with ≥1 prior systemic therapy, with at least SD on the last treatment regimen containing cetuximab or panitumumab and tumor progression within 3 months before enrollment." (PMID 34572729, 2021). "All seven patients KRAS wild type on tumor biopsy were wild type also on urinary LB." (PMID 34680277, 2021). "Recently, studies also demonstrate that tumor mutation burden (TMB) induced antigen exposure, which is a promising biomarker to select NSCLC patients for immunotherapy, specifically in the gene mutation of MET, RET, HER2, and KRAS." (PMID 34887858, 2021). "The four radiomics features model, built using a Random Forest algorithm to diagnose anti-EGFR treatment-sensitive tumors, outperformed both KRAS-mutational status at baseline (AUC = 0.67, p < 0.001) and 8-week tumor shrinkage (RECIST 1.1-like unidimensional tumor shrinkage)." (PMID 33652647, 2021). "Despite a high degree of concordance between the mutational status of KRAS in tumor tissue and ctDNA, ctDNA can sometimes harbor KRAS mutations that are not detected in the primary lesion." (PMID 34572727, 2021). "Activation of KRAS has been shown to depend on the receptor tyrosine kinase (RTK) MAPK/PI3K signaling pathway that has been known to promote the cellular proliferation of the tumor." (PMID 33995628, 2021). "For example, tumor suppressor miRNA may exert their tumor suppressor effects by inhibiting KRAS signaling in RCC." (PMID 34384473, 2021). "The observation that both KRAS splice isoforms are required for tumor growth suggested that they may have different functions in cancer stem and progenitor cells." (PMID 34257283, 2021). "However, in many types of cancer the remaining wild-type KRAS gene can be lost during tumour progression." (PMID 34822010, 2021). "The co-occurrence of mutations may be associated with their presence in specific tumor types, i.e., the APC and KRAS alterations (p < 0.01) in CRC." (PMID 33742104, 2021).
tumor (continued). "However, although it has been proved that VEGF plays an indispensable role in tumor angiogenesis mediated by RAS, seldom do we have studies involving the relationship between KRAS mutations and antiangiogenic therapy efficacy." (PMID 35070984, 2021). "Moreover, we further interrogated the TGCA data base to assess miR-34c-3p and miR-34c-5p expression levels in LUAD/LUSC groups vs. matched, non-tumour counterparts in wild-type KRAS patients." (PMID 32948832, 2021). "Notably, in vivo, KYA1797K significantly suppressed tumor growth and progression both in mouse xenografts of CRC cells harboring APC and KRAS mutations and in the Apcmin/+/KrasG12DLA2 mouse model." (PMID 34065438, 2021). "In the present study, the KRAS gene was among the top mutated genes in patients with both early and late recurrence, regardless of tumor location." (PMID 33919924, 2021). "However, in recent years, KRAS 4A was also proven to be ubiquitously expressed in various cancers and able to increase the adaptability of tumor cells under stress." (PMID 34742312, 2021). "This study was not designed or powered to detect a benefit of panitumumab over other standard of care agents in PDAC which would require a large multicentre study given the rarity of KRAS wild-type tumours and well documented challenges in enrolling patients with PDAC onto clinical trials." (PMID 34956889, 2021). "By acting on downstream effectors, KRAS leads to impaired T-cell recognition of tumor cells, which may mediate immunity escape." (PMID 34616403, 2021). "We discovered a cell-extrinsic mechanism whereby oncogenic KRAS in tumor cells engages with TAMs." (PMID 33833221, 2021). "All our mutation and PD-L1 status was derived from the primary tumor and KRAS mutational subtypes were not collected." (PMID 34518623, 2021). "Both bispecific VHHs induced EGFR specific activation of CD16+ NK cells and tumor cell lysis regardless of KRAS tumor mutation status." (PMID 34771609, 2021). "Here, we identified that gene sets associated with negative regulation upon oncogenic KRAS signaling as well inflammatory responses were downregulated in KPGEMM and KPCRISPR tumor, while tumor cells upregulated MYC target gene signatures and DNA repair pathways." (PMID 33738287, 2021). "Indeed, treatment of bryostatin-1, a potent activator of PKC, effectively phosphorylated Serine 181 of KRAS, mislocalized an oncogenic mutant KRAS from the PM and promoted apoptosis of the mutant KRAS-dependent tumor cells." (PMID 34680072, 2021). "Moreover, the combination therapy identified here has preclinical efficacy against tumor lines with mutant KRAS." (PMID 34862367, 2021). "Therefore, this study sought to specifically investigate the cell-extrinsic role of KRAS in tumor crosstalk with TAMs and the mechanism by which this occurs." (PMID 33833221, 2021). "The expression of KRAS and Ki67 in tumors treated with miRNA agomir was weaker than that in tumor treated with the NC, indicating that KRAS expression might be decreased by miR-30b-5p or miR-30e-5p." (PMID 34336638, 2021). "Although it was initially thought that this was not possible, in recent years, specific inhibitors that bind directly to these proteins have been beginning to emerge, most of them targeting KRAS, since it is one of the most frequently mutant protein in human neoplasia." (PMID 34359657, 2021).
tumor (continued). "Importantly, TST170 was able to detect KRAS variants in the cfDNA of most of the patients (77%) who also had KRAS alterations in their tumor tissue." (PMID 34640513, 2021). "KRAS positive NSCLC patients have recently been considered to be eligible for immune checkpoint blockade plus chemotherapy as first-line regimen as a way to activate anti-tumor immunity but clinical outcomes have been varying." (PMID 33889302, 2021). "Second, a regimen where initial treatment was followed by a treatment pause and continued tumor growth had no influence on the AF of mutated KRAS." (PMID 34271981, 2021). "Overcoming this miRNA-mediated regulation of KRAS expression may also contribute to the mutant KRAS dosage-dependent switch to tumor progression and metastatic spread." (PMID 34591242, 2021). "Hypoxia consequences on KRAS mutant tumours have been investigated with other therapies." (PMID 34298636, 2021). "KRAS not only has an impact on the tumor, but also on its microenvironment." (PMID 34781949, 2021). "Furthermore, studies in animal models have indicated that wild-type KRAS-4A has tumour-suppressive and pro-apoptotic activity, whereas the wild-type KRAS-4B can be characterized as anti-apoptotic." (PMID 34948093, 2021). "Besides these two important GC driver genes, APC and PTEN tumour suppressor driver genes, as well as KRAS and PIK3CA driver oncogenes, were also transversally mutated in both GC histotypes with frequencies below 15% across data sets." (PMID 33724653, 2021). "We found that tipifarnib inhibits CXCL12 expression in pancreatic stellate cells and reduces tumor growth of KRAS WT PDAC in PDX models, suggesting that tipifarnib may benefit a subset of PDAC patients." (PMID 35008248, 2021). "Therefore, we only analyzed patients who were refractory or intolerant to standard chemotherapies [FU, OX, IRI, bevacizumab, and anti-EGFR antibody (if the patients had wild type KRAS/ NRAS tumor)] in order to minimalize the inherent bias." (PMID 33763345, 2021). "An intrinsic (relative) resistance of tumor cells with mutant BRAF or KRAS to chemotherapy may contribute to the poor prognosis that is associated with the presence of these oncogenes." (PMID 34771595, 2021). "It is thought that the worst progression of proximal tumours could be attributed in part to the frequency with which genetic alterations, such as BRAF and KRAS mutations, microsatellite instability, and CpG island methylator phenotype, are detected." (PMID 34557315, 2021). "GFPT1 expression was also increased in tumor tissue, consistent with its regulation by mutant KRAS." (PMID 34844667, 2021). "Measuring the levels of mutational signatures revealed that the cancer-specific distributions of KRAS mutations were influenced, but not determined, by the active mutational processes in the tumor samples." (PMID 33753749, 2021). "We identify autophagy as a defense mechanism in response to FGFR/PLK1 inhibitor‐induced surge of metabolic stress, which is consistent with recent studies showing that KRAS‐driven tumor cells depend on autophagy to help reduce ROS and to provide substrates to fuel cell metabolism." (PMID 34369083, 2021). "Positive cases for KRAS were mostly nonulcerated small SKMs (≤4 mm) without neurotropism and a low number of tumor-infiltrating lymphocytes (TILs) but with a predisposition for microsatellites." (PMID 34769348, 2021). "In addition, we will show how modulation of the immune response and promotion of angiogenesis by oncogenic KRAS can alter the tumor microenvironment (TME)." (PMID 34638560, 2021). "In addition, KRAS signalling enhances the Wnt/β-catenin signalling resulting in tumour multiplicity and progression." (PMID 34044804, 2021).